POLL (DNA polymerase lambda)
Description:
DNA polymerase that functions in several pathways of DNA repair. Involved in base excision repair (BER) responsible for repair of lesions that give rise to abasic (AP) sites in DNA. Also contributes to DNA double-strand break repair by non-homologous end joining and homologous recombination. Has both template-dependent and template-independent (terminal transferase) DNA polymerase activities. Also has a 5'-deoxyribose-5-phosphate lyase (dRP lyase) activity.
Synonyms: BETAN; POLKAPPA
Tractability: Small molecule: a structure with a bound ligand is known; it has a binding pocket of medium quality. PROTAC: ubiquitination databases record sites on it; a small molecule that binds it is known.
Target class: Enzyme
Gene: Protein-coding gene on chromosome 10 (101,576,051 to 101,588,270, reverse strand). Ensembl gene ENSG00000166169.
Subcellular location: Nucleus; Chromosome
Subcellular location (Human Protein Atlas): Nucleoplasm
Pathways (Reactome):
DNA Repair: Nonhomologous End-Joining (NHEJ)
Gene Ontology:
Molecular function: 5'-deoxyribose-5-phosphate lyase activity; DNA polymerase activity; DNA-directed DNA polymerase activity; protein binding; DNA binding; nucleotidyltransferase activity
Biological process: base-excision repair, gap-filling; DNA biosynthetic process; double-strand break repair via homologous recombination; double-strand break repair via nonhomologous end joining; nucleotide-excision repair; DNA replication; somatic hypermutation of immunoglobulin genes; DNA repair
Cellular component: chromosome; nucleoplasm; nucleus; site of double-strand break
Genetic constraint (gnomAD): Loss-of-function variants: 44 observed, 58.76 expected, observed/expected ratio (o/e) 0.75, 90% interval 0.59 to 0.96. The upper end of that interval is the gene's LOEUF score, 0.96, which puts it in group 4 of 6, group 1 being the genes least tolerant of losing a copy. Missense variants: 632 observed, 753.94 expected, observed/expected ratio (o/e) 0.84, 90% interval 0.78 to 0.89. Synonymous variants: 290 observed, 296.81 expected, observed/expected ratio (o/e) 0.98, 90% interval 0.89 to 1.08.
Homologues: Orthologues: chimpanzee POLL (99% identical), macaque POLL (97% identical), pig POLL (87% identical), dog POLL (86% identical), guinea pig POLL (83% identical), mouse Poll (82% identical), rat Poll (82% identical), rabbit POLL (73% identical), tropical clawed frog poll (61% identical), zebrafish poll (56% identical). Paralogues in human: POLM (23% identical), POLB (21% identical), DNTT (21% identical).
Diseases named in the same sentence as POLL in open-access papers:
POLL is named in the same sentence as 7 diseases in open-access papers, as found by Europe PMC text mining. Sharing a sentence is not in itself a finding about the gene and the disease. The quoted sentences say what the papers report.
asthma (1 paper, 2022). "Therefore, these genes can increase the odds and show an up-regulated effect on the outcome of asthma, while 40 genes including CNBP, POLL, ZNF696, HUS1 among others impose a down-regulated effect on the disease response." (PMID 35606385, 2022).
pancreatic cancer (1 paper, 2025). "Utilizing XGBoost and RF, we pinpointed 10 genes closely related to pancreatic cancer, culminating in the identification of RAP1GDS1, TOP2A, ADK, POLL, CD44, and CD4 as pivotal genes linked to hypoxia in pancreatitis." (PMID 40787634, 2025).
pancreatitis (1 paper, 2025). Inflammation of the pancreas. "Further investigations, including differential expression analysis and machine learning techniques, revealed six significant diagnostic markers for pancreatitis: RAP1GDS1, TOP2A, ADK, POLL, CD44, and CD4." (PMID 40787634, 2025). "We then conducted qRT-PCR on serum samples from five pancreatitis patients and five healthy controls to examine the expression levels of RAP1GDS1, TOP2A, ADK, POLL, CD44, and CD4." (PMID 40787634, 2025). "In our study, we identified key hypoxia-related genes—RAP1GDS1, TOP2A, ADK, POLL, CD44, and CD4—in pancreatitis samples using methods such as WGCNA, XGBoost, and RF algorithms." (PMID 40787634, 2025).
pneumococcal meningitis (1 paper, 2016). An acute purulent infection of the meninges and subarachnoid space caused by Streptococcus pneumoniae, most prevalent in children and adults over the age of 60. "The potential role of POLL in B-cell and T-cell differentiation could explain that genetic variation in this gene influences pneumococcal meningitis susceptibility." (PMID 27389768, 2016).
infection (2 papers, 2010 to 2016). The state of being infected such as from the introduction of a foreign agent such as serum, vaccine, antigenic substance or organism. "Taken together, our results strongly suggest that while POLK, POLL and POLH are each capable of supporting cccDNA synthesis at a different efficiency during a de novo HBV infection, POLK plays a more dominant role under the infection conditions examined in this study." (PMID 27783675, 2016).
POLL also shares sentences with these, for which no sentence is quoted: breast carcinoma (2 papers); cancer (2).